PAK1 (p21 (RAC1) activated kinase 1)
Diseases named in the same sentence as PAK1 in open-access papers (continued):
Sharing a sentence is not in itself a finding about the gene and the disease.
breast carcinoma (continued). "For example, endogenous PAK is constitutively activated in certain breast cancer cell lines and ectopic expression of constitutively activated PAK1 in nonmetastatic MCF-7 breast carcinoma cells increased cell motility." (PMID 22848689, 2012). "Pak1 was shown to be activated in breast cancer cells that come from ER negative tumors that overexpress the ErbB2 oncogene." (PMID 23326684, 2012). "Despite the exquisite sensitivity of the breast cancer cell lines harboring genomic copy gains to PAK1 knockdown, inhibition of PAK1 did not generally increase apoptosis of NSCLC cells and xenograft models." (PMID 21653999, 2011). "Based on the observations that Pak1 directly regulates MAPK signaling, and that its expression pattern shows substantial variation in breast cancers, we hypothesized that Pak1 differentially regulates MAPK signaling across our panel of cell lines." (PMID 19317917, 2009). "This Pak1 inhibitory domain (PID) can be used to block Pak1 activity and the biological effects of Pak1 signaling, such as the dissociation of Rac from RhoGDI, GPCR-dependent cell transformation and estrogen-dependent transcription in breast cancer cells." (PMID 17224083, 2006). "However, the precise role of PRL-activated PAK1 in breast cancer and the respective signaling pathways affected is not well defined." (PMID 38660565, 2024). "Therefore, we investigated whether PAK1-mediated ECM uptake and tyrosine catabolism by HPDL were required for breast cancer cell migration on CAF-generated CDM under amino acid starvation." (PMID 38227562, 2024). "Additionally, pTyr-PAK1-dependent secretion of MMP-3 may participate in the extracellular cleavage of E-cadherin leading to the EMT and increased invasion of breast cancer cells." (PMID 38660565, 2024). "Correspondingly, we observed that combined inhibition of Pak1 and CaMKII has a potent synergistic effect in Her2 positive and TNBC cells in vitro, and may represent an attractive therapeutic target for the treatment of breast cancer." (PMID 35111748, 2021). "In addition, since earlier studies on patients with breast cancer reported the role of the combination of PAK1 and CCND1 expressions as a predictor of recurrence-free survival, the relationship between PAK1 alone and the recurrence-free survival rate is unclear." (PMID 33261184, 2020). "Only a few studies exist examining the effect of PAK‐1 inhibition on breast cancer cell growth and none could be found on PAK‐1 expression or inhibition in melanoma." (PMID 31516713, 2019). "To investigate whether PAK1 involved in miR-494-mediated function through MAPK signal pathways, we firstly exam the activation of p38, ERK and JNK MAPK signal pathways in miR-494 overexpressed breast cancer cells." (PMID 28055013, 2017). "However, none of these studies examined the effect of PAK1 inhibition in the genetic profile of breast cancer cells, nor did they use clinically relevant small molecule inhibitors." (PMID 27740936, 2016). "Interestingly, PAK-1 and PAK-2 appear to play opposing roles in models of breast cancer." (PMID 27535340, 2016). "We therefore hypothesized that PAK1 inhibition in combination with microtubule stabilizing chemotherapeutic agent taxanes, such as docetaxel (Taxotere, DTX), could synergistically alter microtubule dynamics in breast cancer cells leading to greater cell death." (PMID 25902869, 2015). "However, given this emerging body of work, a detailed assessment of PAK1 copy number alteration and validation experiments using small molecule inhibitors to evaluate PAK1 catalytic inhibition in breast cancer are still lacking." (PMID 25902869, 2015). "However, determining the direct contribution of EMSY to breast cancer has been difficult because the gene resides within the 11q13-11q14 locus, containing a cassette of genes, including several known and potential breast cancer drivers (CCND1, PAK1, and RSF1)." (PMID 24582497, 2014).
breast carcinoma (continued). "The evidence that PAK1 phosphorylates S305 was indirect and was not confirmed by a direct inspection of the phosphorylation of ERα Ser305 using specific antibodies or by the introduction of a dominant-active PAK1 into breast cancer cells." (PMID 22295213, 2011). "Moreover, in the breast cancer cell, LPA treatment resulted in remarkable production of reactive oxygen species (ROS), while LPA-induced ROS generation, PI3K/PAK1/ERK activation and cell migration could be inhibited by N-acetyl-L-Cysteine, a scavenger of ROS." (PMID 21209852, 2010). "Furthermore, it was shown recently that combination of PAK1 inhibitor (FRAX1036) with taxane treatment could induce microtubule disorganisation, cell cycle arrests and cellular apoptosis in the luminal subtype of breast cancer." (PMID 32752894, 2020). "Our previous study also suggested that prostate cancer cells with the highest expression of PAK‐1 (DU‐145) as well as the breast cancer cells (MCF‐7) were the least susceptible to IPA‐318, raising the concern that the toxicity of IPA‐3 may not be dependent on PAK‐1 expression." (PMID 31516713, 2019). "Interestingly, overexpression of constitutively active PAK1 T423E in non-invasive breast cancer cells stimulates cell motility and anchorage independence, while expression of kinase dead PAK in highly invasive breast cancer cells significantly reduces cell invasiveness." (PMID 27542844, 2016). "However, given that ERα Ser305 phosphorylation can be mediated by at least also PAK1, a group I PAK member, and by PKA, the relative importance of these kinases in breast cancer remains unclear, considering also that both PAK1 and PAK4 have been found overexpressed in human breast cancer." (PMID 26554417, 2015). "As direct interaction between Rac1 and Pak1 or WAVE2 is not detected in breast cancer cells, it is reasonable to assume that βPIX, the Pak-interacting nucleotide exchange factor of Rac/Cdc42, plays an important role in the signal transduction between Rac1 and Pak1." (PMID 22315597, 2012). "Our findings revealed that the levels of PAK1 and HDAC10 were elevated compared to those observed in individuals without breast cancer across various stages of the disease, while the expression level of HDAC6 displayed no significant change." (PMID 40302782, 2025). "As such, the expression of PAK‐1 in cell lines derived from noncancerous breast (MCF‐10A), breast cancer (BT‐474, MCF‐7, MDA‐321, MDA‐468), and melanoma (MDA‐435) was determined using immunoblot analysis." (PMID 31516713, 2019). "In addition, the expression of Pak1 and CaMKII in the non-transformed mammary epithelial cell line MCF10A, and in the breast cancer cell lines MCF7 (luminal), SK-BR3 (Her2 positive) and MDA-MB-231 (triple negative) was assessed by western blot." (PMID 35111748, 2021). "Similar results were obtained in TMX2-28 (estrogen-receptor-negative sub-line of the MCF-7 breast cancer cells) stably overexpressing GFP, myc-PAK1 WT, or myc-PAK1 Y3F (anti-pY397-FAK and anti-FAK blots) indicating that this finding was not restricted to T47D cells." (PMID 27542844, 2016). "Interestingly, the ectopic overexpression of PAK1 in PAK1-non-amplified breast cancer cells recapitulated the sensitivity to combined inhibition of PAK and PARP observed in PAK1-amplified breast cancer cells, suggesting that PAK1 is involved in DNA repair by HR through a FA/BRCA dependent pathway." (PMID 27740936, 2016).
melanoma (44 papers, 2014 to 2025). A malignant, usually aggressive tumor composed of atypical, neoplastic melanocytes. "Activating mutations in KRAS and HRAS are also expected to activate PAK1, although these mutations are present in less than 2% of melanomas each." (PMID 37830586, 2023). "P29S in Rac1 was initially identified as one of the major somatic mutations in human melanoma, shown to enhance Rac1 binding to various effector proteins, including PAK1 (p21 protein activated kinase 1), MLK3 (mixed-lineage kinase 3), and the WRC14,22,23." (PMID 36114192, 2022). "Overexpression of PAK is a known driver of MAPKi resistance, and constitutive activating mutations of RAC1 (RAC1P29S), an upstream effector of PAK1, are found in 10% of MAPKi progression melanoma tumors." (PMID 32346533, 2020). "The P29S mutation was identified as one of the major somatic mutations in melanoma, and was shown to increase the affinity of Rac1 for the effectors PAK1 (p21 protein activated kinase 1) and MLK3 (mixed-lineage kinase 3)." (PMID 28949297, 2017). "PAK1 is amplified and overexpressed in melanoma, and it is strongly associated with wild-type BRAF." (PMID 36830998, 2023). "Furthermore, altered ratio between PAK1 and PAK1Δ15 in melanoma patients was associated with more aggressive disease and with worse prognosis." (PMID 31748572, 2019). "To understand the mechanistic role of JMJD6 in melanoma carcinogenesis, we performed RNA-seq in melanoma cells and found that the alternative splicing of a panel of genes including that encoding for PAK1, a key component of the MAPK signaling pathway, is regulated by JMJD6." (PMID 29187213, 2017). "In melanoma, PAK1 hyperactivation promotes cell survival, proliferation, and immune evasion, contributing to resistance against BRAF and MEK inhibitors." (PMID 40001545, 2025). "p21-Activated kinase 1 (PAK1) inhibition is another pathway that should be further explored as a potential target to enhance sensitivity to targeted therapies in melanoma." (PMID 39534873, 2024). "Identifikovana je povratna sprega LINC00467/miR-485-5p/PAK1, koja je odgovorna za izazivanje pogoršanja melanoma." (PMID 36987414, 2023). "The co-targeting of PAK1 in the context of other melanoma treatments appears as a worthwhile direction for future exploration, with a potential to tangibly improve the management of this deadly malignancy." (PMID 37830586, 2023). "PAK1 mRNA splicing in melanoma is skewed towards producing the kinase-proficient isoform of the protein." (PMID 37830586, 2023). "Melanomas commonly display elevated levels of PAK1 expression as well as its activity, with the latter being judged by the abundance of the appropriately phosphorylated form." (PMID 37830586, 2023). "The feedback loop LINC00467/miR-485-5p/PAK1 was identified, which was responsible for inducing melanoma deterioration." (PMID 36987414, 2023). "Identifikovana je povratna sprega LINC00467/miR-485-5p/PAK1, koja je odgovorna za izazivanje pogor{anja melanoma." (PMID 36987414, 2023). "Here, we review the reports that implicate p21-regulated kinase 1 (PAK1) and PAK1-related pathways in the response of melanoma to various therapeutic modalities." (PMID 37830586, 2023). "LINC00467 stimulates proliferation, migration and invasion capacities of melanoma through targeting miR-485-5p to upregulate PAK1, which is a possible therapeutic target for melanoma." (PMID 36987414, 2023). "Treatment with cisplatin in melanoma induces RhoJ expression and in turn it activates PAK1 by phosphorylation at Ser199." (PMID 36830998, 2023). "LINC00467 stimuliše kapacitete proliferacije, migracije i invazije melanoma putem ciljanja miR-485-5p da bi se pojačao PAK1, koji pruža potencijalne mete za lečenje melanoma." (PMID 36987414, 2023).
melanoma (continued). "Taken together, a novel feedback loop was identified that LINC00467/miR-485-5p/PAK1 induced melanoma deterioration." (PMID 36987414, 2023). "LINC00467 stimulates proliferation, migration and invasion capacities of melanoma via targeting miR-485-5p to upregulate PAK1, which provides potential targets for treatment of melanoma." (PMID 36987414, 2023). "Accordingly, there is mounting evidence that the concomitant inhibition of PAK1 enhances the potency of various anti-melanoma regimens." (PMID 37830586, 2023). "While the preponderance of evidence points to PAK1 inhibition as a promising strategy to augment various types of anti-melanoma therapies, the need for a clinically usable approach to PAK1 regulation remains unmet." (PMID 37830586, 2023). "Overexpression of PAK1 in melanoma cells remarkably enhanced EdU-stained cell ratio, migratory cell rate and invasive cell rate." (PMID 36987414, 2023). "Admittedly, these connections between PAK1 and the apoptotic machinery have been predominantly investigated in non-melanoma models, and their relevance to life/death decisions in melanoma cells is yet to be rigorously established." (PMID 37830586, 2023). "Melanomas with BRAF class 1 mutations harbored fewer amplifications of GAB2 (FDR = 0.099), CCND1, and PAK1 (both FDR = 0.18)." (PMID 35706047, 2022). "RAC1 through PAK1, Merlin and the cytoskeleton renders the melanoma cells a higher metastatic potential and higher proliferation rate of metastatic cells." (PMID 34827551, 2021). "For example, RhoJ is overexpressed in metastatic melanoma and treatment of melanoma cell lines with cisplatin was found to promote PAK1 autophosphorylation in a RhoJ-dependent manner." (PMID 32309283, 2020). "In BRAF-mutant melanomas, the activation of PAK1 is contribute to the acquired drug resistance to BRAFi and combined BRAFi and MEKi therapies." (PMID 32863957, 2020). "PAK1 activation can contribute to chemoresistance in melanoma through the inhibition of pro-apoptotic signaling pathways." (PMID 32309283, 2020). "In line with this, PAK1 was shown to promote melanoma chemoresistance by suppressing DNA-damage-sensing pathways." (PMID 30454561, 2018). "Recently, the melanogenic role of PAK1 has been revealed by silencing the PAK1 gene in melanoma cells, explaining why a series of PAK1 blockers have been found to be useful for brightening skin." (PMID 28098826, 2017). "We then infected B16F10 cells, a melanin-producing mouse melanoma cell line, with lentiviruses carrying control shRNA or Jmjd6 shRNA, and/or infected with retroviruses carrying vector or expression plasmids for PAK1, PAK1Δ15, JMJD6, or JMJD6m." (PMID 29187213, 2017). "In both melanoma cell lines and patient derived cell strains a positive correlation was observed between the level of PAK1 protein expression and cell invasiveness." (PMID 27765920, 2016). "Our findings complement this work, providing further evidence that PAK1 is important in invadopodia formation in melanoma." (PMID 27765920, 2016). "PAK1 copy number alterations have also been observed in other tumor indications, such as ovarian cancer and melanoma and further validation efforts are necessary to apply the findings reported here to these other indications." (PMID 25902869, 2015). "The pan-Pak inhibitor PF3758309 has been shown to suppress the growth of several Pak1-dependent cancers such as colon, breast, squamous cell, and melanoma." (PMID 25596744, 2015). "In skin cancer, which included basal cell carcinoma, cutaneous squamous cell carcinoma, melanoma (including acral, metastatic, and cutaneous subtypes), and desmoplastic melanoma, PAK1 had the highest frequency of alterations (4%), all of which were amplifications." (PMID 39756822, 2025). "Similarly, in BRAF-mutant melanomas, PAK1 activation drives resistance by engaging the AKT signaling pathway." (PMID 40001545, 2025).
melanoma (continued). "However, in melanoma, PAK1 activation contributes to tumor cells’ resistance to DNA-damaging agents, enhancing their tolerance to damage and promoting resistance to conventional chemotherapeutic agents." (PMID 39534873, 2024). "Overall, the available information on the functions of PAK1, the experimental data from preclinical melanoma models, and the evidence from similarly treated non-melanoma cancers all point to PAK1 as a modulator of melanoma’s response to multiple types of anti-cancer therapy." (PMID 37830586, 2023). "QRT-PCR data suggested that level of PAK1 remarkably increased in melanoma cells and tissues." (PMID 36987414, 2023). "The recognition of the role of PAK1 in many BRAF wild-type cutaneous melanomas has brought about the question of whether it plays a similar role in the GNA-driven uveal form of the disease." (PMID 37830586, 2023). "Overall, ample evidence suggests that PAK1 by itself is a critical vulnerability in a sizeable subset of melanomas, while its co-targeting has the potential to enhance MAPK-directed targeted therapies and circumvent many common modes of resistance to the latter." (PMID 37830586, 2023). "Importantly, it was also reported that PAK1 can suppress the sensing of DNA damage and increase the tolerance of melanoma cells to genotoxic treatment." (PMID 37830586, 2023). "Mutations in the KIT gene, encoding receptor tyrosine kinase c-KIT, are typically found in acral and mucosal melanomas and may be predicted to activate a PAK1-mediated oncogenic pathway, as was documented in other malignancies." (PMID 37830586, 2023). "Overall, the available information suggests that a safe and effective inhibition of PAK1-dependent molecular processes would enhance the potency of the currently available anti-melanoma treatments, although considerable challenges in implementing such strategies still exist." (PMID 37830586, 2023). "Here, PAK1 was found to be responsible for the carcinogenic role of LINC00467 in melanoma." (PMID 36987414, 2023). "PAK1 inhibition results in the sensitization of BRAF-mutant melanoma to a BRAF inhibitor." (PMID 36830998, 2023). "PAK1 is overexpressed in a subset of BRAF wildtype melanomas." (PMID 34827551, 2021). "The observation that PAK1 depletion sensitized melanoma cell lines to cisplatin suggests that combination treatments of PAK1 inhibitors and DNA-damaging agents may improve chemoresponsiveness in certain human tumors." (PMID 32309283, 2020). "A recent study demonstrated that melanoma cells carrying the RAC1P29S mutation exhibit an augmented engagement of PAK1 (an immediate downstream effector of RAC1) in the presence of the RAC1P29S mutant and are thus highly sensitive to the PAK1 inhibitor." (PMID 32545340, 2020). "In addition, BRAF mutant melanoma cell lines, PAK1 has been shown to phosphorylate the pro-apoptotic protein Bad, preventing its association with Bcl-2 and the subsequent release of cytochrome C from mitochondria." (PMID 32309283, 2020). "This study expanded these findings to other cancers (breast and melanoma) by testing the hypothesis that genetic and pharmacological inhibition of PAK‐1 alters cell growth, migration, and invasion in prostate, breast, and skin cancer cell lines." (PMID 31516713, 2019). "The results showed that overexpression of JMJD6, but not JMJD6m, in melanoma A375 cells was associated with an increased level of the full length PAK1 mRNA and a decreased level of PAK1Δ15 mRNA." (PMID 29187213, 2017). "We detected a decreased level of the full length PAK1 in JMJD6-depleted melanoma cells." (PMID 29187213, 2017). "Therefore, using three different experimental assays we have demonstrated that reducing PAK1 or PAK4 expression can inhibit the invasion of melanoma cells." (PMID 27765920, 2016). "PAK1 inhibitor may have a prominent role in the treatment of melanoma with wild-type BRAF cells." (PMID 36830998, 2023).